TAS2R20 (taste 2 receptor member 20)
Description:
Receptor that may play a role in the perception of bitterness and is gustducin-linked. May play a role in sensing the chemical composition of the gastrointestinal content. The activity of this receptor may stimulate alpha gustducin, mediate PLC-beta-2 activation and lead to the gating of TRPM5 (By similarity).
Synonyms: T2R49; T2R56; TAS2R49; T2R20
Tractability: Antibody: its Gene Ontology location is reachable by antibodies, with high confidence; UniProt predicts a signal peptide or a membrane-spanning region. PROTAC: a small molecule that binds it is known.
Target class: Membrane receptor; Taste receptor (taste family GPCR); Taste family G protein-coupled receptor
Gene: Protein-coding gene on chromosome 12 (10,995,961 to 10,998,304, reverse strand). Ensembl gene ENSG00000255837.
Subcellular location: Membrane
Pathways (Reactome):
Signal Transduction: Class C/3 (Metabotropic glutamate/pheromone receptors); G alpha (i) signalling events
Sensory Perception: Sensory perception of sweet, bitter, and umami (glutamate) taste
Gene Ontology:
Molecular function: bitter taste receptor activity; G protein-coupled receptor activity
Biological process: detection of chemical stimulus involved in sensory perception of bitter taste; G protein-coupled receptor signaling pathway; sensory perception of taste
Cellular component: membrane; plasma membrane
Genetic constraint (gnomAD): Loss-of-function variants: 1 observed, 0.26 expected, observed/expected ratio (o/e) 3.81. That is too few expected variants to judge how well the gene tolerates losing a copy. Missense variants: 364 observed, 369.36 expected, observed/expected ratio (o/e) 0.99, 90% interval 0.9 to 1.08. Synonymous variants: 136 observed, 133.2 expected, observed/expected ratio (o/e) 1.02, 90% interval 0.89 to 1.18.
Homologues: Orthologues: chimpanzee TAS2R20 (99% identical), macaque TAS2R20 (85% identical), dog CAFA-T2R43 (58% identical), mouse Tas2r120 (49% identical), rat Tas2r120 (46% identical), rat Tas2r136 (45% identical), mouse Tas2r136 (44% identical). Paralogues in human: TAS2R46 (69% identical), TAS2R30 (68% identical), TAS2R19 (67% identical), TAS2R43 (67% identical), TAS2R31 (66% identical), TAS2R50 (62% identical), TAS2R14 (42% identical), TAS2R13 (41% identical), TAS2R7 (37% identical), TAS2R9 (36% identical), TAS2R10 (34% identical), TAS2R8 (32% identical), and 11 more.
Diseases named in the same sentence as TAS2R20 in open-access papers:
TAS2R20 is named in the same sentence as 17 diseases in open-access papers, as found by Europe PMC text mining. Sharing a sentence is not in itself a finding about the gene and the disease. The quoted sentences say what the papers report.
breast carcinoma (3 papers, 2021 to 2022). "The TAS2Rs with highest expression in HNSCC (TAS2R4, TAS2R14, TAS2R19, TAS2R20, TAS2R30, TAS2R43, and TAS2R45) overlap with TAS2Rs expressed at increased levels in breast cancer." (PMID 34717036, 2022).
cervical squamous cell carcinoma (1 paper, 2022). A squamous cell carcinoma arising from the cervical epithelium. "Notably, statistically significant survival associations were identified for TAS2R5 in cervical squamous cell carcinoma (p < 0.001), TAS2R20 in esophageal adenocarcinoma (p = 0.044), and TAS2R4, TAS2R20, and TAS1R3 in prostate adenocarcinoma (p = 0.03, p = 0.033, and p = 0.023, respectively)." (PMID 35624283, 2022).
colon cancer (1 paper, 2024). "Utilizing univariate Cox regression analysis, we identified seven TAS2Rs genes associated with prognosis in colon cancer patients, including TAS2R4, TAS2R5, TAS2R14, TAS2R19, TAS2R20, TAS2R31, and TAS2R38." (PMID 38999959, 2024). "Our results show that compared to normal colon tissue, the expression levels of multiple bitter taste receptor genes are elevated in colon cancer tissue, including TAS2R4, TAS2R5, TAS2R14, TAS2R19, TAS2R20, TAS2R31, and TAS2R38." (PMID 38999959, 2024). "Differential expression analysis results revealed that compared to normal colon tissue, colon cancer samples exhibited elevated expression levels of TAS2R1, TAS2R4, TAS2R5, TAS2R14, TAS2R19, TAS2R20, and TAS2R38 (p < 0.05), with the exception of TAS2R60, which was downregulated." (PMID 38999959, 2024).
diabetes (1 paper, 2025). "The rs117458236 variant in TAS2R20 remained associated with infection in individuals with diabetes (OR: 3.27; CI: 0.93, 8.91; p = 0.035) or cardiovascular disease (OR: 2.69; CI: 1.10, 5.65; p = 0.016)." (PMID 41153757, 2025).
tumor (2 papers, 2019 to 2022). "Changes in expression for TAS1R1, TAS1R3, TAS2R4, TAS2R5, TAS2R14, TAS2R19, and TAS2R20 had survival associations in at least one tumor histology." (PMID 35624283, 2022). "Some GPCRs have low median expression (<1 TPM) in the tumor population in general (e.g., taste receptors TAS2R14 and TAS2R20 in ESCA) but may be expressed in subsets of these populations, wherein they may contribute to differences in survival." (PMID 31765370, 2019).
infection (1 paper, 2025). The state of being infected such as from the introduction of a foreign agent such as serum, vaccine, antigenic substance or organism. "The rs117458236 variant, located in the 3′ untranslated region (UTR) of TAS2R20, was associated with a trend toward increased odds of confirmed/probable infection (OR: 1.95, CI: 0.98, 3.51; p = 0.039)." (PMID 41153757, 2025). "The rs117458236 variant associated with infection is located in the 3′ untranslated region (UTR) of TAS2R20." (PMID 41153757, 2025). "One allele in TAS2R20 was associated with a trend to an increased risk of confirmed or probable infection." (PMID 41153757, 2025).
TAS2R20 also shares sentences with these, for which no sentence is quoted: cancer (1 paper); cardiovascular disease (1); COVID-19 (1); esophageal adenocarcinoma (1); inflammation (1); kidney clear cell carcinoma (1); neurodegenerative disease (1); Parkinson disease (1); prostate adenocarcinoma (1); respiratory diseases (1); upper respiratory infections (1).